GSTP1 (glutathione S-transferase pi 1)
Diseases named in the same sentence as GSTP1 in open-access papers (continued):
Sharing a sentence is not in itself a finding about the gene and the disease.
breast carcinoma (continued). "To date, researches have reported the correlation of GSTP1 Ile105Val polymorphisms with breast cancer risk and chemosensitivity Several studies have reported that women with the GSTP1 105Val genotype in Shanghai of Southeast China, America, and India have greater breast cancer risks." (PMID 23826324, 2013). "Another previous study determined the frequency of aberrant methylation of GSTP1 candidate gene in primary breast cancer tissue for patients with predominantly advanced cancers and suggested that GSTP1 is potentially important in the early diagnosis of breast cancer." (PMID 24565108, 2013). "ESR1 and GSTP1 methylation could be important in the development of these high-grade male breast cancers." (PMID 22765268, 2012). "In this study, aberrant methylation of RASSF1, APC and GSTP1 were both frequent as well as early events in the progression continuum from normal to benign to invasive cancer and support a monoclonal transformation continuum to breast cancer progression." (PMID 21776373, 2011). "This analysis showed that the patients in this cohort with unmethylated GSTP1 (HR: 7.52, CI: 1.76-32.07, p = 0.006) and FOXC1 (HR: 7.32, CI: 1.11-48.31, p = 0.039) showed a higher risk of dying from breast cancer compared with patients methylated for the same genes." (PMID 20338046, 2010). "GSTP1 has been found to be frequently methylated in different stages of breast carcinomas." (PMID 20056007, 2010). "In support of this hypothesis it has been shown that GSTP1 expression correlates with doxorubicin resistance in breast cancer cell lines." (PMID 20338046, 2010). "Therefore, in postmenopausal patients, an increased breast cancer risk is linked to the mutant GSTO2 genotype alone, whereas in premenopausal women, the combined presence of GSTP1 and GSTO2 may further elevate the risk." (PMID 40724836, 2025). "Interestingly, GSTP1 has been found unmethylated and overexpressed in lung and breast cancer." (PMID 37548362, 2023). "Additionally, breast cancer cells were rescued from apoptosis by overexpressing GSTP1." (PMID 33946704, 2021). "Moreover, the transfer of EVs from adriamycin-resistant breast cancer cells (which had increased levels in GSTP1 mRNA - coding for a drug-detoxifying enzyme) increased GSTP1 expression and induced resistance in recipient cells in an EV concentration-dependent manner." (PMID 32384712, 2020). "We investigated whether GSTT1 (“null” allele), GSTM1 (“null”allele), GSTP1 (A313G), RFC1 (G80A), MTHFR (C677T), TS (2R/3R) polymorphisms were associated with toxicity and survival in patients with early breast cancer (EBC) treated with adjuvant chemotherapy (CT)." (PMID 28747156, 2017). "The results indicated that GSTP1 promoter methylation probably plays an important role in breast carcinogenesis, which could serve as an effective biomarker for the diagnosis and monitor of breast cancer." (PMID 26585467, 2015). "Thus, aberrant GSTP1 promoter methylation could be a helpful biomarker for the early screening of breast cancer." (PMID 26585467, 2015). "Heterogeneous DNA methylation patterns in the GSTP1 promoter constitute a major obstacle to the implementation of DNA methylation-based analysis of GSTP1 and might explain some of the contradictory findings in the analysis of the significance of GSTP1 promoter methylation in breast cancer." (PMID 26393654, 2015). "We discovered large differences in the performance of the different technologies, and the identified heterogeneous DNA methylation patterns might explain some of the contradictory findings in the analysis of the significance of GSTP1 promoter methylation in breast cancer." (PMID 26393654, 2015). "Thus, the role of GSTP1 in breast cancer is also controversial." (PMID 23826324, 2013).
breast carcinoma (continued). "GSTP1 status after neoadjuvant treatment with DNMTi may also be a useful prognostic marker, similar to the prognostic significance of Ki67 after neoadjuvant treatment with endocrine and chemo-therapies in breast cancer." (PMID 21980513, 2011). "For example, NBDHEX treatment inhibited GSTP1-1 activity, and co-administration of adriamycin and NBDHEX promoted apoptosis of adriamycin-resistant breast cancer cells." (PMID 39125992, 2024). "Patients with breast cancer were almost three times more likely to have been exposed to RARB and GSTP1 methylation than controls (OR = 2.81; 95% CI [1.02–8.22]; p = 0.026)." (PMID 37548362, 2023). "One of the first studies that proposed the use of epigenetic biomarkers in plasma to detect breast cancer compared four methylation biomarkers, APC, GSTP1, RASSF1A, and RARB, in primary breast cancer tissue and plasma samples." (PMID 36765815, 2023). "SRC/GSTP1 expression and G6PDY249/322 phosphorylation were positively correlated in breast cancer tissues characterized to be ER (+) and PR (+) or HER (-); however, this correlation was not evident in ER(-)/PR(-) or ER(-)/PR(+) or HER (+) tumor tissues." (PMID 37491277, 2023). "Further, the IP-enriched SRC/GSTP1 protein and G6PDY249/322 Tyr phosphorylation status were strongly and positively correlated with the breast cancer that exhibit ER expression and PR expression, to which our experimental cell line MCF-7 belongs." (PMID 37491277, 2023). "In studies using MCF7 breast cancer cells, a significant decrease in NO-mediated iron release from cells by the GSH transporter, MRP1, was observed in GSTP1-overexpressing MCF7 cells." (PMID 36139130, 2022). "AKR1B1, RASGRF2, CRMP1, BNIP3, GSTP1, HOXA5 and PAX6 genes were methylated in ER-positive and HER2-negative breast cancer with ALNM." (PMID 36454866, 2022). "It was concluded that GSTP1 interacts with glyceraldehyde-3-phosphate dehydrogenase (GAPDH) and increases its enzyme activity in breast cancer cells." (PMID 33946704, 2021). "GSTP1 was found to be upregulated in CLDN6-overexpressing and multidrug-resistant estrogen-receptor positive (ER+) breast cancer cells." (PMID 33946704, 2021). "The FOSL1,GSTP1 and CCND1 genes are located at11q13, a cytoband commonly affected by CNA in breast cancer, with relevantfunction in progression and invasion." (PMID 30816904, 2019). "In this study, we evaluated the copy number of FOSL1, GSTP1,CCND1 in different subtypes of breast carcinomas, classified accordingto the status of hormone receptors, ER and PR, KI-67, and HER2 protein." (PMID 30816904, 2019). "For example, several attempts have been made to use genes that are commonly hypermethylated in breast tumors (GSTP1, RASSF1A, RARβ, APC, and DAPK) to generate a blood-based breast cancer methylation signature." (PMID 29614786, 2018). "For instance, an eight gene promoter hypermethylation panel (APC, BRCA1, BIN1, CST6, GSTP1, P16, P21, and TIMP3) had a reported sensitivity of 90% for identifying breast cancer patients." (PMID 29614786, 2018). "Previous studies showed that glutathione S-transferase Pi 1 (GSTP1) is a critical metabolic driver that is heightened specifically in triple negative breast cancer (TNBC) and drives breast cancer pathogenicity." (PMID 28978147, 2017). "In ADM resistance breast cancer cell line MCF-7/ADR, upregulation of GSTP1 confers resistance to ADM." (PMID 29116019, 2017). "MS-HRM analysis was carried out to determine the methylation status of CCND2, DAPK1, GSTP1, HIN-1, MGMT and RASSF1A promoters in tumor tissues and histologically normal-appearing tumor-adjacent and tumor-distant tissues of 17 breast cancer patients." (PMID 26370119, 2015). "When we applied the MS-HRM methods to biopsy samples of breast cancer patients, the promoters of CCND2, GSTP1, HIN-1 and RASSF1A were generally found to be methylated homogeneously." (PMID 26370119, 2015).
breast carcinoma (continued). "CCND2, DAPK1, GSTP1, HIN-1, MGMT and RASSF1A were selected because they have previously been reported to be frequently methylated in primary breast cancers." (PMID 26370119, 2015). "For breast cancer, methylation has been noted in genes including BRCA1, p16, E-cadherin, H-cadherin, ATM, CST6, cyclin D2, PTEN, RASSF1A, APC, RARb2, GSTP1, ER, PR, as well as numerous other genes related to multiple pathways relevant for carcinogenesis." (PMID 24368439, 2014). "In the present study, five genes, ABCB1, FOXC1, GSTP1, PPP2R2B and RASSF1A were hypermethylated already in early stage breast cancer (stage I and II)." (PMID 24093668, 2013). "The five most frequently methylated TSGs (RASSF1, APC, CDH13, GSTP1, and CDKN2B) were the same in all groups of breast cancer and, with the exception of CDKN2B, were involved in other tumors from LS patients, too, although with variable frequencies." (PMID 22691310, 2012). "Using hierarchical clustering in the plasma samples cohort, we found significant promoter hypermethylation of eight genes (APC, BIN1, BRCA1, CST6, GSTP1, P16, P21 and TIMP3) in patients' plasma of breast cancer patients compared with plasma of normal subjects." (PMID 21283676, 2011). "Breast cancer specific survival was significantly improved in patients with methylated promoters for ABCB1, GSTP1 and FOXC1 (p = 0.004, p = 0.004 and p = 0.021 respectively)." (PMID 20338046, 2010). "To assay the role of GSTP1 and HPV-16 E7 in cell survival after UV exposure, we used two cellular models: 1) the HaCaT cells and 2) the MCF-7 human breast carcinoma cell line." (PMID 19826491, 2009). "SNP-SNP interactions in breast cancer development have been also reported in other studies, which targeted the SNPs of the carcinogen metabolism genes, including GSTM1, GSTT1, GSTP1, GSTM3 and CYPs." (PMID 16672066, 2006). "Overexpression of GSTP1 triggers autophagy through interacting with the p110α subunit of phosphatidylinositol-3-kinase (PI3K) and subsequently inhibits the PI3K/AKT/mTOR signaling to protect human breast cancer cells from adriamycin (ADR)-induced cell death." (PMID 37958442, 2023). "Notably, TNFRSF10B, GSTP1, and PDIA3 were found to interact with the target proteins of current medications used in prostate or breast cancer treatment." (PMID 37735436, 2023). "Targeted bisulfite sequencing showed that the promoter methylation levels of AKR1B1, BNIP3, CRMP1, GSTP1, HOXA5, PAX6, and RASGRF2 were increased in ER-positive and HER2-negative breast cancers with ALNM, compared with ER-positive and HER2-negative breast cancers without ALNM." (PMID 36454866, 2022). "Furthermore, in addition to highly methylated AKR1B1, RASGRF2 and CRMP1 gene promoters, BNIP3, GSTP1, HOXA5 and PAX6 gene promoters were also methylated in ER-positive and HER2-negative breast cancer with ALNM." (PMID 36454866, 2022). "Moreover, in addition to highly methylated AKR1B1, RASGRF2 and CRMP1 gene promoters, BNIP3, GSTP1, HOXA5 and PAX6 gene promoters were also methylated in ER-positive and HER2-negative breast cancer with ALNM." (PMID 36454866, 2022). "In breast cancer, the presence or absence of GSTP1 expression predicts response to cytotoxic chemotherapy, particularly to the taxanes docetaxel and paclitaxel." (PMID 34191807, 2021). "Interestingly, among DEGs, a relevant number of genes involved in oxidative metabolism (e.g. GSTP1, CYP4Z1, AKR1B10) and in different pathways affecting breast cancer behavior (WNT5A), was observed." (PMID 33863935, 2021). "This study also showed that EVs isolated from the serum of breast cancer patients who did not respond to chemotherapy had higher GSTP1 levels than EVs from patients who responded to the treatment." (PMID 32384712, 2020). "Postmenopausal women with GST polymorphisms leading to low or no GSTT1, GSTP1 and GSTM1 activity benefitted to a greater extent from the consumption of marine ω3 fatty acids in the context of breast cancer." (PMID 31505792, 2019).
breast carcinoma (continued). "In a previous study, we determined the promoter methylation status of six tumor suppressor genes (CCND2, DAPK1, GSTP1, HIN-1, MGMT and RASSF1A) in tumor, tumor-adjacent and tumor-distant tissues from breast cancer patients and normal breast tissues from healthy controls." (PMID 28403857, 2017). "Finally, we analyzed the correlation between GSTP1 and CLDN6 expression in 40 human breast cancer tissues by using immunohistochemistry." (PMID 29116019, 2017). "Further analysis of genes associated with breast cancer, including ABCB1, BRCA1, GSTP1, IGF2, and TERT, showed a high CM fraction in cancer but non-CM in normal cell lines." (PMID 26659027, 2015). "Methylation-sensitive high-resolution melting was used to screen promoter methylation in a panel of 13 genes reported as methylated in breast cancer (RASSF1A, TWIST1, APC, WIF1, MGMT, MAL, CDH13, RARβ, BRCA1, CDH1, CDKN2A, TP73, and GSTP1) in 29 tumour pairs (16 ipsilateral and 13 contralateral)." (PMID 26452468, 2015). "The most frequently methylated genes were RASSF1 (65%), APC (43%), CDH13 (35%), GSTP1 (17%), and CDKN2B (17%), and the pattern was quite similar in breast carcinomas from mutation carriers, non-carriers and sporadic ductal cases." (PMID 22691310, 2012). "The unmethylated GSTP1 promoter present in MDA-MB-231 breast cancer cells was not digested by BstUI or HhaI." (PMID 21980513, 2011). "The FOXC1 methylation status might be a widely applicable prognostic factor for breast cancer patients while the methylation status of ABCB1 and GSTP1 might be a predictive factor for doxorubicin and perhaps anthracycline treatment in general." (PMID 20338046, 2010). "There is an absence of data regarding this issue, although earlier work did show that prevention of breast cancer relapse with radiation therapy was greatest among women with elevated levels of GST π protein in tumor tissue, supporting a role for GSTP1 in response to radiation therapy." (PMID 16848913, 2006). "Furthermore, we observed that variant carriers of GSTP1 rs1138272 and FGD4 rs10771973 had marginally higher rates of health-related benefits than non-carriers after breast cancer diagnosis." (PMID 39302578, 2025). "Forced expression of the enzyme in GSTP1-negative breast cancer cells confers docetaxel resistance." (PMID 34191807, 2021). "Absence of GSTP1 expression is found in approximately two thirds of the patients with breast cancer, suggesting it might play an important role in breast carcinogenesis." (PMID 26585467, 2015). "ESR1 methylation and GSTP1 methylation were not significantly correlated with poor survival in our group of male breast cancer and therefore do not seem to be useful prognostic biomarkers in male breast cancer." (PMID 22765268, 2012). "To achieve a gene panel for developing a breast cancer blood-based test we quantitatively assessed the DNA methylation proportion of 248 CpG sites per sample (total of 31,248 sites in all analyzed samples) on 10 candidate genes (APC, BIN1, BMP6, BRCA1, CST6, ESR-b, GSTP1, P16, P21 and TIMP3)." (PMID 21283676, 2011). "Smaller studies have reported that smoking did not modify associations between GSTT1, GSTM1, or GSTP1 polymorphisms and breast cancer, whereas former smokers with GSTT1 null were found to have an increased risk of breast cancer compared with never smokers with GSTT1 present." (PMID 19440493, 2009). "Furthermore, in addition to highly methylated AKR1B1, RASGRF2 and CRMP1 gene promoters, BNIP3, GSTP1, HOXA5 and PAX6 gene promoters were also methylated in ER-positive and HER2-negative breast cancer with ALNM, which may serve as candidate methylation biomarkers." (PMID 36454866, 2022). "Here we report aberrant methylation levels of ABCB1, FOXC1, GSTP1, PPP2R2B and RASSF1A in DCIS and stage I-IV providing evidence that suggests that changes in methylation level is an early event and may also be important in progression to later stages of breast cancer." (PMID 24093668, 2013).
breast carcinoma (continued). "And compared with ER-positive and HER2-negative breast cancers without ALNM, the methylation levels of AKR1B1, RASGRF2, CRMP1, BNIP3, GSTP1, HOXA5, and PAX6 promoter were increased in ER-positive and HER2-negative breast cancers with ALNM." (PMID 36454866, 2022). "It was observed that lycopene (2 μM for 1 week) upregulated the expression of GSTP1 and has the ability to demethylate GSTP1 promoter in MDA-MB-468 cell line; however, the scenario is not similar in MCF-7 breast cancer cells." (PMID 29681985, 2018). "Double-negative breast tumors exhibited frequent hypermethylation in APC, GSTP1, RASSF1A, and TWIST, revealing the presence of epigenetic differences between double-negative breast tumors and breast cancers expressing either HER2/neu or ER." (PMID 18485221, 2008). "Double negative (ER-negative, HER2/neu-negative) breast cancers had significantly lesser frequencies of RASSF1A, GSTP1, and APC methylation (P < 0.0001, P < 0.0001, and P = 0.0035, respectively)." (PMID 18485221, 2008). "Moreover, promoter regions of candidate genes like GSTP1 and RARB are hypermethylated in most patients with breast cancer, regardless of the cancer stage." (PMID 37548362, 2023).